HIF1A (hypoxia inducible factor 1 subunit alpha)
Diseases named in the same sentence as HIF1A in open-access papers (continued):
Sharing a sentence is not in itself a finding about the gene and the disease.
tumor (continued). "Furthermore, thyroid hormones modulate the transcription of multiple tumor-associated genes —such as HIF1A, VEGF, FGF2, PDGF, EGFR, MMP, and NOS2—all of which are implicated in the regulation of angiogenesis." (PMID 41153831, 2025). "A study showed that YY1 could suppress anti-tumor immunity by enhancing HIF-1α stability in tumor-associated macrophages." (PMID 40867514, 2025). "HIF-1α overexpression is linked to tumor growth and apoptosis prevention by overcoming hypoxia." (PMID 41020852, 2025). "However, prolonged or excessive HIF-1α activity has been linked to inflammation, tissue remodeling, and tumor progression." (PMID 40453108, 2025). "Furthermore, the presence of lactic acid in the TME would also promote the M2-like polarization of tumor-associated macrophages through activating HIF-1α signaling, contributing to the orchestration and maintenance of the immunosuppressive TME." (PMID 41041050, 2025). "Tumor hypoxia, a hallmark of solid tumors, drives aggressive behavior and therapeutic resistance through stabilization of hypoxia-inducible factor 1-alpha (HIF1α), which regulates genes involved in angiogenesis, metabolism, and immune evasion." (PMID 41463265, 2025). "Recent studies have highlighted the involvement of STUB1 in various human malignancies, as it regulates the stability and activity of several tumor-associated transcription factors, such as CRIP1, YAP1, HIF-1α, and c-Myc, thereby influencing tumor growth, invasion, metastasis, and angiogenesis." (PMID 40859326, 2025). "Biomarkers such as HIF-1α, vascular endothelial growth factor, glucose transporter 1, and carbonic anhydrase IX are linked to hypoxia-driven tumor behaviors and may serve as indicators of disease aggressiveness and patient outcomes." (PMID 40901111, 2025). "Moreover, hypoxia, another important feature of the metabolic microenvironment, regulates tumor-associated angiogenesis through the HIF-1α signaling pathway, thereby inhibiting CAR T-cell invasion into tumor tissues." (PMID 41226585, 2025). "HIF-1α was correlated with tumor size, and COX-2 was associated with metastasis and staging." (PMID 40011266, 2025). "The increase in EGFR expression caused by HIF1a expression, associated with targeted drug delivery to the tumor, may justify the sensitization to cetuximab." (PMID 40149887, 2025). "Besides being mainly expressed by tumor cells, the stabilization of hypoxia‐inducible factor 1‐alpha (HIF1α) also causes CA IX overexpression in prostate CAFs, leading to the epithelial–mesenchymal transition in tumor cells." (PMID 40569831, 2025). "However, HIF-1α-deficient macrophages exhibited enrichment of M2 phenotype markers and reduced cytotoxicity to tumor cells, suggesting a relationship between HIF subunits and macrophage polarization." (PMID 40746883, 2025). "Cancer cell-derived lactate can induce the expression of vascular endothelial growth factor (VEGF) and arginase 1 (Arg1) through HIF-1α signaling pathway, which promotes the polarization of tumor-associated macrophages (TAMs) toward the M2 phenotype, enabling TAMs to promote tumor growth." (PMID 38287402, 2024). "We found that in the tissue cohort CXCL12 expression was strongly correlated with differentiation, CEA & TTF-1 protein expression, CD44v6 was associated with tumor stage and chromogranin protein expression and HIF1A & KRT7 showed positive correlation with CEA expression alone." (PMID 38877052, 2024). "Since BOH NPs showed superior oxygen-independent PDT effects in vitro, the tumor model we established was confirmed at a severe hypoxic state by immunofluorescence staining based on a hypoxia-associated protein, hypoxia-inducible factor 1-α (HIF-1α)." (PMID 38514624, 2024). "Loss of HIF‐1α enhances tumor progression and immune cell infiltration." (PMID 39415849, 2024). "Furthermore, HIF-1α is implicated in the acquisition of metastatic behavior, suggesting a potential link between tumor cell hypoxia and metastasis." (PMID 39408832, 2024).
tumor (continued). "Moreover, this same group also characterized legumain (LGMN) as a key protease that is transcriptionally regulated by HIF1α and enriched in tumor-associated macrophages." (PMID 38994360, 2024). "In the context of HIF, HIF-1α is primarily implicated in the acute hypoxic process of the tumor." (PMID 39204162, 2024). "Therefore, a close correlation has been observed between TAMs and HIF-1α in the development of tumor-associated angiogenesis." (PMID 38602536, 2024). "HIF-1α has been associated with GBM tumor progression and treatment resistance, among others." (PMID 39055895, 2024). "The TME serves as a critical component in the activation and immunosuppressive function of MDSCs, and emerging evidence suggests that hypoxic conditions within the tumor, particularly through the HIF-1α-associated pathway, play a significant component in this process." (PMID 38720342, 2024). "Thus, EZH2 indirectly promotes the buildup of HIF-1α, which causes tumor cells to dedifferentiate by blocking PHD3." (PMID 38911968, 2024). "Thus, the reduction in both primary tumor growth and spontaneous lung metastases we observed with eKET diet administration —and their association with reduced Hif1a gene expression —are consistent with prior findings from the Wu lab." (PMID 39410010, 2024). "HIF-1α expression is strongly linked to aggressive tumour phenotype and poor prognosis in GC." (PMID 39816318, 2024). "The fact that PF139 also harbors KRAS mutation may also raise interesting questions about the association of oncogenic KRAS and HIF1α in tumor progression." (PMID 39227650, 2024). "Furthermore, GPx2KD/HIF1α caused dramatic upregulation of p63 in hybrid tumour cell populations at the primary tumour and lung mets." (PMID 38238426, 2024). "Through HIF-1α pathway mediation, tumor cells upregulate genes associated with glycolysis, energy metabolism, angiogenesis, tumor cell survival, and red blood cell production, including vascular endothelial growth factor (VEGF), GLUTs, and other glycolytic enzymes." (PMID 38994113, 2024). "Since mTOR has been linked to reprogramming tumor metabolism and increasing levels of hypoxia-inducible factor 1 α (HIF-1α), we hypothesized that LMP2A would increase HIF-1α levels to enhance ATP generation in B lymphoma cell lines." (PMID 38612754, 2024). "Thus, it was shown that high HIF-1α expression is associated with regional and distant tumor cell metastases, advanced tumor stage, depth of infiltration, positive surgical margins, and poor overall survival." (PMID 38727811, 2024). "Furthermore, the inactivation of AMPK causes the stabilization of HIF-1α and a glycolytic shift in tumor cells in vitro." (PMID 38255314, 2024). "Furthermore, patients with higher expressions of VPS35 and HIF-1α frequently associated with larger tumor size; while higher expression of GLA was indicative of worse T stage, N stage and AJCC stage." (PMID 38528532, 2024). "Results showed the correlation between CXCL12 and differentiation grade, CEA and TTF-1 protein expression, CD44v6 was associated with tumor stage, chromogranin expression whereas HIF1A and KRT7 were significantly associated with CEA protein expression in the metastatic tissues." (PMID 38877052, 2024). "Moreover, previous studies have reported that HIF-1A functions as a tumor suppressor in ccRCC, whereas HIF-2A has been implicated as an oncoprotein in ccRCC." (PMID 38360682, 2024). "Tumor type and grade are the criteria for risk stratification of tumors, which is more accurate when combined with molecular and immunohistochemical indicators, and it has been demonstrated that HIF-1α is a high-risk factor for recurrence of EC." (PMID 39723370, 2024). "RT could activate immunosuppressive signalling pathway by the induction of HIF-1a, which stimulates PD-L1 expression in tumour cells, tumour-associated macrophages and dendritic cells (Ref." (PMID 39438247, 2024).
tumor (continued). "Besides MYC, a second TF, hypoxia-inducible factor-1α (HIF-1α), controls tumor cell glycolysis under oxygen deficient conditions." (PMID 37450923, 2024). "Moreover, this IL-6-dependent increase of VEGF expression in tumor cells is linked with the higher HIF-1α in LECs." (PMID 38361941, 2024). "Furthermore, tumor cell autophagy has been observed to be associated with HIF-1α expression, contributing to a poor prognosis and the promotion of chemoresistance in cancer." (PMID 38339408, 2024). "The loss of tumor suppressor LKB1 can promote the MR of cancer cells through HIF-1α." (PMID 39588377, 2024). "There exists an important statistical correlation between the overexpression of HIF-1α and enlargement in tumor size, which means HIF-1α has a potential diagnostic role and maybe a novel auxiliary diagnostic indicator." (PMID 39744628, 2024). "For example, a subset of Hif1a−/− NK cells exhibited potent antitumor activity, and a seven-gene signature and a tumor-associated subpopulation in tumor-infiltrating NK cells were defined and correlated with tumor prognosis and immunotherapy resistance." (PMID 38538718, 2024). "HIF-1α inhibition has also been shown to abrogate PD-L1 mediated immune evasion by suppressing PD-L1 expression on tumor cells and tumor-associated macrophages, thereby fostering the implementation of combination therapies based on HIF inhibitors and anti-PD-L1 monoclonal antibodies." (PMID 38175205, 2024). "SDH deficiency is linked to tumor progression, with succinate accumulation stabilizing HIF-1α." (PMID 39765841, 2024). "HIF-1α is an oxygen-inducible factor that is implicated in various physiological and pathological conditions, including cancers such as HNCs, where it promotes tumor growth, angiogenesis, and resistance to chemo and radiotherapy." (PMID 39684225, 2024). "Production of mtROS caused by loss of BNIP3 induced cell proliferation and tumor growth, increased gene expression of HIF1α-dependent glycolysis and angiogenesis, suppressed oxidative phosphorylation, suggesting BNIP3 plays an inhibitory role in mammary tumorigenesis." (PMID 37407961, 2023). "We also suggest that the circadian clock affects anti-tumor immunity by regulating immune-associated functions, such as depletion of T cells, enhancement of immune escape, and controlling the metabolic process of TAMs by affecting the function of Hif-1α." (PMID 36647780, 2023). "So far, it is known that the mTOR signaling cascade can affect HIF-1α translation and stimulation of this pathway, for example by growth factors, hormones, or oncogenes/tumor suppressor mutations, which can lead to HIF-1α synthesis, even under normoxic conditions." (PMID 37371055, 2023). "This was in accordance with Cui and Jiang who concluded that HIF-1α expression was an independent factor predicting poor OS and that HIF-1α expression was significantly associated with older age, larger tumor, high grade, positive nodal involvement and TNM stage in TNBC." (PMID 36939902, 2023). "Finally, we studied the distribution difference of risk genes between tumor cells and normal cells and the correlation between HIF1A and risk genes in a hypoxia environment." (PMID 37081097, 2023). "The present study provides convincing data to establish an enhanced anti-tumor effect of paclitaxel caused by combining flubendazole via HIF1α/PI3K/AKT signaling pathways for BC therapy, which contributes to reducing the clinical dose of paclitaxel, thus diminishing baneful adverse reactions." (PMID 37894802, 2023). "In addition to tumor growth and invasiveness, increased hif-1α expression is associated with decreased sensitivity to chemotherapy and radiation therapy (Rankin and Giaccia, 2008)." (PMID 37534226, 2023). "Moreover, the observation of inflammation-triggered tumor promotion and neoangiogenesis-induced metastatic capacity led to the search for a possible functional link between the major tumor-associated marker proteins NF-κB and HIF-1α in their activated forms." (PMID 37583906, 2023).
tumor (continued). "Conversely, the loss of HIF-1α activity resulted in reduced tumor expansion." (PMID 37175841, 2023). "Although Honokiol increased mitochondrial oxygen consumption rate and reduced ROS synthesis in wild-type cells, it further increased ROS production in tumor cells, which caused dysregulated ROS homeostasis and inhibition of HIF-1α, and finally induced apoptotic or autophagic death." (PMID 36678567, 2023). "In general, HIF-1α overexpression is associated with a poor prognosis and tumor progression." (PMID 37095487, 2023). "HIF-1α overexpression was significantly associated with increased tumor size (p = 0.046)." (PMID 36766555, 2023). "Anti-inflammatory TAM markers (TREM2 and CD32a) are linked with tumour hypoxia (HIF-1α)." (PMID 37324244, 2023). "Additionally, HIF-1α is believed to play an important role in tumor-associated inflammatory signaling." (PMID 38273861, 2023). "HIF-1α induces metastasis, which is the primary cause of tumor-related deaths." (PMID 36891273, 2023). "In addition, the activation of HIF-1α under hypoxic conditions is associated with tumour grade and poor prognosis in HGGs." (PMID 37174088, 2023). "In addition, high HIF1α was linked with poor TLS density in the tumor-invading front and in inner tumor areas (p = 0.003 and p = 0.01, respectively)." (PMID 36586079, 2023). "Similarly, HIF1A expression in human tumor-infiltrating NK cells is negatively associated with their antitumor function, highlighting the potential function of HIF1α inhibitors in cancer therapy." (PMID 36742317, 2023). "In addition, as a major transcriptional regulator of tumor cell response to hypoxia, HIF-1α can interact with histone deacetylase 1 (HDAC1) and cause immune dysfunction." (PMID 37921852, 2023). "Indeed, HIF-1α signaling was shown to upregulate PD-L1 expression in murine splenic and tumor-associated myeloid cells (MDSCs)." (PMID 36845555, 2023). "Additionally, high HIF1α was linked with poor TLS density in the tumor-invading front and in inner tumor areas." (PMID 36586079, 2023). "Increased HIF-1α activity results from loss of function of the VHL tumour suppressor gene." (PMID 36661719, 2023). "To determine whether the anti-tumor effects of tipifarnib were associated with HIF-1α, we focused on energy metabolism, particularly ROS production in cancer cells." (PMID 37511305, 2023). "A tumor-specific splicing variant of macrophage receptor with collagenous structure (MARCO) promotes metabolic dysregulation resulting in a hypoxic tumor microenvironment by regulating the HIF-1α signaling." (PMID 37845393, 2023). "Conversely, HIF-1α loss inhibits tumor growth in xenograft studies." (PMID 37684337, 2023). "HIF-1α is a key transcriptional regulator in the cell oxygen signaling pathway that can activate downstream target genes to cause the proliferation, metastasis, and invasion of tumor cells and accelerate disease progression." (PMID 37762463, 2023). "STAT3 has also been reported to induce the expression of HIF-1α and cause tumor angiogenesis." (PMID 37239383, 2023). "The upregulation and stabilization of HiF-1α within cancer cells have been closely associated with increased tumor and cell survival, heightened angiogenesis, enhanced proliferation of cancer cells, and elevated resistance to both chemotherapy and radiation therapies." (PMID 38063756, 2023). "Hence, nanoceria potently blocked the induction of HIF-1α to VEGF signalling pathway under hypoxia which is associated with aggressive tumour progression and metastasis." (PMID 36656411, 2023). "Although the precise mechanism is still unknown, the difference in HIF1A expression between the high-risk and low-risk groups may be related to the two groups' different tumor immune microenvironments." (PMID 37716978, 2023).
tumor (continued). "Analysing the associations between hypoxic TME and tumor prognosis, the current work demonstrated significant associations between high HIF-1α expression and large tumor size, poorly differentiated and advanced stage cases, positive LVI and high Ki-67 proliferation index." (PMID 36939902, 2023). "In addition, HIF1A was associated with increased tumor immunity and aggressive phenotypes in human cancers." (PMID 35359830, 2022). "Accumulating evidence has shown that hypoxia is a common phenomenon in the growth of solid tumor, and CHMP4A acts as the modulator to increase the expression level of hypoxia-inducible factor-1 α protein (HIF-1α), promoting the tumor progression in a hypoxia-associated pro-tumor mechanism." (PMID 36267972, 2022). "Similarly, the regulation of HIF-1α during cellular responses has been implicated in angiogenesis and tumor development." (PMID 35745677, 2022). "As a result, ascorbate-deficient cells may have an enhanced HIF1-α function, possibly leading to tumor development." (PMID 35745630, 2022). "Next, we conducted IHC assays to investigate the micro-vessel density of tumors in the four groups and found that GSK3α markedly promoted tumor angiogenesis, although this could be inhibited by loss of HIF1α." (PMID 35292059, 2022). "Furthermore, HIF-1α induced by hypoxia has been implicated in the rapid differentiation of MDSCs into TAMs in the tumor microenvironment." (PMID 36578780, 2022). "Moreover, we found that tumor sizes of ≥ 1.0 cm along with increased HIF-1α expression were independent predictors of the risk of capsule invasion." (PMID 36329448, 2022). "High expression of STATs, HIF-1α, and mTOR has an important role in causing local hypoxia in tumors, forming a hypoxic barrier, tumor neovascularization, promoting tumor cell proliferation, and negatively regulating immunity and a series of other tumor-promoting events." (PMID 36119517, 2022). "In ovarian cancer, the overexpression of HVEM (TNFRSF14), a member of the TNF receptor superfamily, is associated with the activation of AKT/mTOR signaling, promoting the expression of Bcl-2 and HIF-1α, which is positively associated with tumor proliferation and negatively related to cell apoptosis." (PMID 36358792, 2022). "Most studies have examined the expression of HIF-1α suggesting that it would be associated with higher pathologic grade and tumor stage, higher MVD (microvascular density), higher rate of metastasis, poorer overall survival, poorer disease-free survival and poor response to chemotherapy." (PMID 35158767, 2022). "Increased expression of HIF-1α is closely associated with tumor progression in various cancers." (PMID 35198082, 2022). "Multiple signaling pathways, including the angiogenesis, hypoxia, and VEGF pathways were significantly enriched, which encouraged us to further explore the underlying mechanism by which swimming attenuates tumor angiogenesis and the HIF-1α/VEGFA pathway activation." (PMID 35291563, 2022). "Decreased expression of HIF-1α targeted genes, including the encoding vascular endothelial growth factor, leads to the reduction of tumor vessel size and vascular density, thus playing an anti-tumor role." (PMID 36397350, 2022). "Here, we aim to determine whether tumour HIF-1α-positivity and hypoxic gene-expression signatures associated with the benefit of radiotherapy, and outcome." (PMID 35140341, 2022). "Therefore, in tumor diagnosis and treatment, some studies have developed HIF1α pharmacogenomic mutation models to study individual changes in the effects of tumor hypoxia drugs, which will guide precise treatment." (PMID 35860430, 2022).